IL13 (interleukin 13)
Diseases named in the same sentence as IL13 in open-access papers (continued):
Sharing a sentence is not in itself a finding about the gene and the disease.
Airway obstruction (30 papers, 2008 to 2025). Obstruction of conducting airways of the lung. "These cells are heterogeneous and a subset of CD8+ cells was reported to produce IL13 and was associated with airway obstruction suggesting a plausible role of these cells in airway remodelling." (PMID 36685493, 2022). "In the lung, increased IL-13 expression is extensively associated with airway hyper-responsiveness such as inflammation, mucous hypersecretion, epithelial fibrosis, and airway obstruction." (PMID 31790411, 2019). "Type 2 cytokines, such as IL-13, play an important role in the development of airway obstruction driving epithelial hyperplasia, GC hypertrophy, mucous hypersecretion, and loss of polarity with aberrant migration." (PMID 40446022, 2025). "Th2 cells generate the proinflammatory cytokines IL-4, IL-5, and IL-13, which trigger mast cell and basophil activation, leading to inflammation and airway obstruction." (PMID 39421735, 2024). "IL-13 stimulates goblet cell hyperplasia and mucus hypersecretion, and can exacerbate airway obstruction." (PMID 33884360, 2021). "When combined with IL-13, IL-4 can promote goblet cell hyperplasia of the airway, and those goblet cells secrete excessive mucus leading to airway obstruction, breathing difficulties, and even death in asthmatic patients." (PMID 33343229, 2020). "Licochalcone A had the ability to reduce goblet cell hyperplasia, reducing excessive secretion of mucus and preventing airway obstruction and asphyxia by blocking expression of IL-4 and IL-13 in BALF and lung tissue." (PMID 31226782, 2019). "IL-13 induces many features of allergic lung disease, including goblet cell metaplasia and mucus hypersecretion, which all contribute to airway obstruction." (PMID 26385707, 2015). "In addition of effects on ASM contractility, the effect of IL-13 on baseline RL and Cdyn may be attributable structural changes such as bronchial fibrosis, goblet cell hyperplasia, and associated mucus hypersecretion causing airway obstruction." (PMID 20957211, 2010). "IL-13 induces multiple features of allergic lung disease, including metaplasia and mucus hypersecretion, contributing to airway obstruction." (PMID 18564432, 2008). "Mechanistically, oxidative stress and mitochondrial dysfunction, such as ATP release and signaling, may contribute to worsened airway obstruction induced by both PMa and IL-13 exposures." (PMID 37448802, 2023). "Mucus hypersecretion is forced by IL-13, and airway obstruction by mucus can lead to cough and dyspnea; therefore, Camellia can prevent mucus hypersecretion by control of IL-13 and may be useful in control of cough, especially in asthmatic patients." (PMID 33884360, 2021). "Interleukin 5 (IL-5) and 13 (IL-13) regulate airway obstruction, hyperreactivity, and remodeling." (PMID 30542075, 2018). "For example, IL13, a cytokine secreted by T helper type 2 (Th2) cells, can induce many features of allergic lung disease including airway hyper-responsiveness, goblet cell metaplasia, and mucus hyper-secretion, which all contribute to airway obstruction." (PMID 28302172, 2017). "Both airway obstruction and inflammation are associated with TH2 cytokines, including IL-13." (PMID 27156176, 2016). "Given that RSV induces a TSLP-dependent, IL-13–producing ILC2 response in mice and that IL-13 promotes airway obstruction, it is intriguing to consider the therapeutic potential of an anti-TSLP mAb for treating severe RSV infection." (PMID 27156176, 2016). "In experiments and analysis of Janet S Lee's team, there was a positive correlation between IL-13 concentration in the cycle and the severity of airway obstruction and diffusion impairment, and a negative correlation between intracellular IL-13 and FEV1%." (PMID 32280354, 2020).
Stroke (29 papers, 2014 to 2026). Sudden impairment of blood flow to a part of the brain due to occlusion or rupture of an artery to the brain. "Our research reveals for the first time that IL-13 improves long-term neurological deficits and white matter damage caused by stroke, which provides pre-clinical rationale for the application of IL-13 in future investigations of stroke." (PMID 35578342, 2022). "Intranasal administration of IL-13 after tMCAO attenuated sensorimotor and cognitive deficits, which correlated with a decrease in white matter damage, lending further support that loss of white matter integrity is strongly linked to poor stroke outcomes in ischemic stroke patients." (PMID 35578342, 2022). "Additionally, immunostaining with MBP and SMI32 3 days after tMCAO showed that IL-13 did not reduce the demyelination damage caused by tMCAO during the acute phase of stroke, suggesting that IL-13 may promote white matter repair after tMCAO." (PMID 35578342, 2022). "Notably, we wanted to investigate whether IL13-producing MSC were able to convert stroke-associated neuroinflammatory immune responses into an alternatively activated inflammatory response." (PMID 29866203, 2018). "Stroke significantly increased the levels of IL-13 and IFN-γ in the ischemic brain at 1 w and 2 w post-tMCAO." (PMID 39578419, 2024). "In the present study, we observed a significant increase in IL-13 expression in the subacute ischemic mouse brain after stroke (1 w and 2 w post-tMCAO)." (PMID 39578419, 2024). "Peripheral administration of IL-13, for example, reduced stroke-induced brain injury and improved sensory and motor functions in mice." (PMID 39578419, 2024). "IL‐13 and IL‐4 have been shown to increase IL‐6 production, and elevations in both IL‐13 and IL‐4 demonstrate reparative effects following stroke in mice models." (PMID 36478506, 2023). "This study also found that IGF-1 treatment inhibited levels of inflammatory cytokines such as TNF-α, IL-1β, and IL-6 at 4 h after stroke, while only IL-6 and IL-13 continued to be inhibited at 24 h after stroke, as did chemokines GRO-KC and CCL2." (PMID 37638322, 2023). "Genes involved in key signaling processes after stroke, including Il-10, Il-12, Hmgb1, Il-13, p38 MAPK, HIF1α, Stat3, and Il-4, were inhibited by NPD1 + RvD1." (PMID 37270727, 2023). "Intranasal delivery of IL-13 enhanced the structural and functional integrity of white matter after stroke." (PMID 35578342, 2022). "IL-13 exerts an effect on microglia and infiltrating macrophages in the brain after stroke, and it can regulate the spontaneous polarization transition from anti-inflammatory to pro-inflammatory phenotype of microglia and macrophages." (PMID 35173738, 2022). "This immunomodulation of local Mφs/microglia by IL-13 is in line with previous stroke and TBI reports." (PMID 35488301, 2022). "Meanwhile, IL-13 treatment significantly reduced the tMCAO-induced increase in the g-ratio across different axon diameters suggesting that IL-13 maintained axonal myelination or promoted axonal remyelination after stroke." (PMID 35578342, 2022). "Overall, IL-13 treatment suppressed the pro-inflammatory response and promoted the anti-inflammatory response in the stroke brain." (PMID 35578342, 2022). "IL13 is the well-characterized promoter of M2 polarization in microglia and macrophages, inducing a M1-to-M2 phenotype shift in the subacute phase of stroke." (PMID 36330425, 2022). "IL13 behaves as an anti-inflammatory cytokine, regulating microglia and macrophage post-stroke responses." (PMID 36330425, 2022). "Post-treatment with IL-13 improved long-term neurofunctional recovery and decreased brain tissue atrophy after stroke." (PMID 35578342, 2022). "Our investigation thus provides a pre-clinical rationale for the application of IL-13 as a potential treatment for stroke." (PMID 35578342, 2022).
Stroke (continued). "Previous studies examining the effect of IL-13 against stroke have focused on its effects on microglia/macrophage activation and short-term functional recovery." (PMID 35578342, 2022). "IL-13 (60 μg/kg) was administered intranasally starting 2 h after stroke and continued for seven consecutive days." (PMID 35578342, 2022). "Our recent animal stroke model showed that interleukin (IL)-4 and IL-13 released by microglia are converted into monocyte-derived macrophages." (PMID 35634277, 2022). "In animal models of TBI and stroke, IL-13 treatment also facilitated anti-inflammatory effects and reduced neuronal cell loss." (PMID 35488301, 2022). "CatWalk automated gait analysis system was used to detect possible IL-13-induced motor improvements post-stroke." (PMID 31372938, 2019). "As compared to the vehicle-treated stroke animals, IL-6 expression levels were markedly upregulated in the PI samples from the animals treated with IL-13 (p = 0.0055)." (PMID 31372938, 2019). "Control MSC and IL13-MSC grafts are able to survive in the pro-inflammatory stroke environment and display a similar remodeling pattern." (PMID 29866203, 2018). "Another important observation to be taken into account here is the expression and accumulation of major histocompatibility complex class II (MHC-II) following MSC and IL13-expressing MSC engraftment after stroke." (PMID 29866203, 2018). "We also assessed the effects of STAT3 inhibition with stattic on sensorimotor and cognitive function to explore whether it mimicked the neuroprotective effects of IL-13 in stroke mice." (PMID 35578342, 2022). "To ascertain whether IL-13 suppressed the inflammatory response by inhibiting STAT3 activation in the stroke brain, we firstly assess that IL-13 whether directly inhibit the STAT3 activity in vitro using rat primary microglia culture." (PMID 35578342, 2022). "Next, we explored the possible cellular mechanism of the protective effect of IL-13 after stroke." (PMID 35578342, 2022). "Therefore, in the present study, we investigated the effect of IL-13 on ischemic stroke in a mouse tMCAO model up to 35 days post-stroke." (PMID 35578342, 2022). "This suggests that although IL-4 and IL-13 share the same receptor, they may function through completely different cells after a stroke." (PMID 35578342, 2022). "Therefore, immunomodulation with interleukin-13 is a promising approach to promote long-term functional recovery after stroke." (PMID 35578342, 2022). "Interestingly, interleukin-13 can also improve ischemic liver gluconeogenesis and hyperglycemia in stroke model rats, exerting a salutary action." (PMID 35173738, 2022). "The long-term neuroprotective effects of IL-13 after stroke remain largely unexplored." (PMID 35578342, 2022). "Inflammation plays an important role in cerebral ischemic injury, therefore we explored whether IL-13 treatment correlated with induction of anti-inflammatory genes and/or downregulation of pro-inflammatory genes in the stroke brain." (PMID 35578342, 2022). "Finally, the adhesive removal test displays yet another improvement of the stroke-induced sensorimotor deficits in the IL-13-treated group." (PMID 31372938, 2019). "As seen for IL-37, several other anti-inflammatory markers, namely Foxp3 (P = 0.012), Ym1 (P = 0.006), Il-10 (P = 0.018), Il-13 (P = 0.002) and Tgfb (P = 0.008) were up to 3-fold increased in the ischemic hemisphere following stroke in IL-37tg compared to WT mice." (PMID 31061403, 2019). "Whether IL-13 treatment is efficient at a clinically relevant time point in more severe models of ischemia where acute post-stroke immunosuppression is observed remains unknown." (PMID 31372938, 2019). "Furthermore, at the same time point post-stroke, there was a decrease in delay of removing the adhesive between contra- and ipsilateral side following IL-13 treatment, and this difference nearly reached statistical significance (p = 0.0517)." (PMID 31372938, 2019).
Stroke (continued). "By continuous secretion of IL-13 via MSCs, we could enhance and prolong the expression of neuroprotective and anti-inflammatory marker Arg-1 until week 2 after stroke induction." (PMID 29866203, 2018). "Therefore, to drive microglia and macrophages towards a more protective anti-inflammatory phenotype after stroke, we selected the immunomodulatory cytokine interleukin 13 (IL13), which is a well-known modulator of immune responses in vitro and in vivo." (PMID 29866203, 2018). "Interestingly, IL-13 showed a protective effect on sensorimotor dysfunction until 35 days after tMCAO, especially in the acute phase of stroke (3, 5 days after tMCAO), as shown by increased latency to fall off the rotating rod and decreased number of left turns in the corner test." (PMID 35578342, 2022). "However, there are few reports regarding IL-13’s participation in stroke." (PMID 31164999, 2019). "Interestingly, we observed a significantly increased expression of F4/80 by CCR2RFP/+ macrophages upon IL13-MSC transplantation as compared to F4/80 expression by CCR2RFP/+ macrophages following stroke or stroke + control MSC grafting (p = 0.008 and p = 0.007)." (PMID 29866203, 2018). "In our study, the salivary concentration of IL-2, IL-5, IL-7, IL-10, IL-12 (p70), IL-13, IL-15, and IFN-α2 was below the detection level in healthy controls (most commonly) and in stroke patients." (PMID 40520895, 2025). "In addition, aspirin may be helpful in reducing the inflammation associated with stroke by targeting pro-inflammatory proteins described in this study, such as lipocalin-2, IP-10 and SAA or by targeting and promoting anti-inflammatory proteins such as IL-13." (PMID 33930055, 2021). "Here, we also found that levels of IL-1β, IL-1RA, IL-10, IL-13, IL-15, Flt-3L, Fractalkine, EGF, G-CSF and GM-CSF were lower in the severe stroke group." (PMID 31164999, 2019). "In our present investigation, we have not analyzed the influence of continuous secretion of the anti-inflammatory cytokine IL-13 and/or M2 polarized microglia and macrophages on the survival of autologous MSC grafts after stroke." (PMID 29866203, 2018). "In BALB/c mice at 1 week post-stroke G-CSF, IP-10, KC, MCP-1, MIP-1α, and MIP-1β were increased, and levels of IL-1β, IL-10, and IL-13 were decreased compared to sham mice." (PMID 27600707, 2016). "At 24 hours post-stroke, IGF-1 treatment continued to inhibit selective pro-inflammatory markers, such as IL-6, the pleitrophic cytokine IL-13 and the chemoattractants CCL2 and GRO-KC." (PMID 24618563, 2014). "IL-13 is a Th2 cytokine that is a known driver of an alternatively activated state in immune cells and is widely applied as an immunomodulatory therapeutic in preclinical studies of SCI, traumatic brain injury, MS and stroke." (PMID 40893377, 2025). "Because of this reputed role, along with its limited expression in the stroke brain and the lack of clarity regarding its biological role, we did not examine the role of IL-13Rα2 in IL-13 signaling in the present study." (PMID 35578342, 2022). "We hereby proved that intranasal IL-13 treatment neither changed the infiltration of peripheral immune cells, which enters the brain to participate in central immunity after a stroke, nor did it change the immune cell population in blood, spleen and lung." (PMID 35578342, 2022). "We observed lower levels of IL-13 in children with TBM and with stroke patients, which may suggest involvement of dysregulated inflammation." (PMID 33930055, 2021). "We determined whether the procedure of cell grafting (MSC or IL13-MSC) into the ischemic brain influences the motor and sensory performance after stroke in mice." (PMID 29866203, 2018). "The expression of IL-13 in the striatum has not yet been investigated in stroke." (PMID 39578419, 2024). "However, it must be noted that in a severe, permanent carotid artery occlusion model of stroke, simultaneous deletion of IL-13, IL-9, IL-4, and IL-5 did not worsen the neurological outcome." (PMID 36639371, 2023).
Stroke (continued). "qPCR analysis of the PI area in the stroke brains at 3 dpi revealed a significant increase of major alternative activation markers Arg1 (p = 0.0408) and Ym1 (p = 0.0122), but not Fizz1/Rentla (data not shown) upon IL-13 treatment." (PMID 31372938, 2019). "Next, we assessed whether microglia and/or macrophage activation, based on F4/80 expression, was altered upon transplantation of IL13-producing MSC, as compared to the situation after transplantation of MSC alone or without any transplantation after stroke induction." (PMID 29866203, 2018).